MATN3 (matrilin 3)
Diseases named in the same sentence as MATN3 in open-access papers (continued):
Sharing a sentence is not in itself a finding about the gene and the disease.
tumor (continued). "Upregulated genes included cartilage-associated genes (COMP, MATN3, and COL11A2), collagen- and extracellular matrix-associated genes (COL9A2, SFRP2, and SERPINE2), and tumor metastasis- and progression-associated genes (SLC38A3, FST, ITGA11, and DGKI)." (PMID 36192442, 2022). "Clinical analyses unveiled that high MATN3 expression was related to age, tumor status, and clinical stages." (PMID 34900024, 2021). "The tissue distribution and cell location of VCAN, CLIP4 and MATN3 proteins suggest their relevance to the tumor microenvironment (TME) 27-29." (PMID 32754268, 2020). "The tissue distribution and cell localization of the VCAN, CLIP4 and MATN3 proteins suggest their relevance to the tumor microenvironment (TME)." (PMID 32754268, 2020). "The rationale for selecting MATN3 as a target lies in its demonstrated overexpression in multiple cancer types and its established role as both a prognostic marker and a contributor to tumor progression." (PMID 41004439, 2025). "It suggests that MATN3 may play divergent roles in different tissue environments, possibly related to distinct regulatory networks or the tumor microenvironment." (PMID 41004439, 2025). "We found that MATN3 may be involved in the regulation of tumor development through its effect on the PI3K-Akt signaling pathway." (PMID 39991588, 2025). "These tools assess the levels of various immune cells within the tumor microenvironment, providing a broader understanding of how MATN3 might influence or be influenced by immune dynamics." (PMID 41004439, 2025). "Importantly, patients with positive tumor status and advanced clinical stages exhibited a higher level of MATN3." (PMID 34900024, 2021). "Therefore, we infer that the effect of VCAN, CLIP4 and MATN3 expression on the poor survival of GC patients is probably related to the remodeling of stromal components in the tumor microenvironment." (PMID 32754268, 2020). "Furthermore, the positive correlation between MATN3 and various immunosuppressive genes, checkpoint inhibitors, and chemokines in several cancer types implies a potential involvement in immune evasion and regulation of the anti-tumor immune response." (PMID 41004439, 2025). "Seven genes of the prognostic model (COPA, GPX7, ITGB5, MATN3, MCM7, MMP1, and SPP1) have been validated to be related to tumor progression, whereas the remaining three genes, BNDF, GADD45B, and LOX, need to be further analyzed." (PMID 35699863, 2022). "The results showed the expression level of PON1, MATN3, and SERPINE1 were increased in the tumor tissues." (PMID 35372408, 2022). "We obtained the expression of MATN3 in tumor tissues and normal tissues from TIMER2.0 in a variety of cancer types, and combined the TCGA database + GTEx database to explore the expression of MATN3 in pan-cancer." (PMID 39991588, 2025). "MATN3 expression exhibits a significant negative correlation with tumor purity in several types of cancer, including PCPG, CHOL, BLCA, COAD, READ, and STAD." (PMID 41004439, 2025). "Second, the expression of MATN3 was not confirmed in tumor specimens from our cohort, and in vitro and in vivo analyses were not conducted to explore the tumor-related function of MATN3 in GC progression." (PMID 34900024, 2021).
cancer (14 papers, 2019 to 2025). A tumor composed of atypical neoplastic, often pleomorphic cells that invade other tissues. "Despite the diverse types of alterations observed across different cancers, the overall mutation frequency of MATN3 remains relatively low, with the wild-type allele being predominant in most cases." (PMID 41004439, 2025). "Continuing our comprehensive analysis of MATN3, we examined its association with patient survival outcomes across multiple cancer types." (PMID 41004439, 2025). "Subsequent RNA sequencing of α-Pinene-treated HepG2 and Hep3B cells revealed a notable downregulation of MATN3, a gene previously associated with poor prognosis in various cancers." (PMID 41004439, 2025). "The enrichment analyses shed light on the potential mechanisms underlying MATN3’s functions in cancer." (PMID 41004439, 2025). "We found that cancer-associated fibroblasts (CAFs) exhibit a strong positive correlation with MATN3, similar to endothelial cells." (PMID 41004439, 2025). "Delving into the genetic landscape of MATN3, our mutational analyses revealed diverse patterns of copy number variations, amplifications, and mutations across different cancer types." (PMID 41004439, 2025). "Extending our research through a comprehensive pan-cancer analysis, we confirmed the association between high MATN3 expression and poor prognosis across multiple cancer types." (PMID 41004439, 2025). "Our findings highlight the importance of context and cancer specificity in the development of targeted therapies and further validate the relevance of exploring the mechanisms underlying MATN3 expression modulation by agents like α-Pinene." (PMID 41004439, 2025). "The primary objective of this study was to investigate whether α-Pinene can regulate the expression of MATN3 (Matrilin-3), a gene previously associated with poor prognosis in various cancers." (PMID 41004439, 2025). "We also found that MATN3 had high diagnostic value in all 15 cancer types and could play a great role in cancer diagnosis." (PMID 39991588, 2025). "Interestingly, we observed a significant downregulation of MATN3, a gene previously associated with poor prognosis in various cancers." (PMID 41004439, 2025). "We found that MATN3 may be associated with prognosis and immunity in different cancer patients in our previous explorations, and we used the STRING database and the GeneMANIA database to construct the PPI interaction network as well as the GGI interaction network of MATN3." (PMID 39991588, 2025). "Unraveling the intricate mechanisms underlying MATN3’s functions could unveil novel therapeutic avenues and contribute to the development of personalized treatment strategies tailored to the unique molecular landscapes of different cancer types." (PMID 41004439, 2025). "Interestingly, in these cancers, higher MATN3 expression is associated with poorer prognosis." (PMID 41004439, 2025). "The stacked bar chart illustrates the frequency of copy number variations (CNVs) affecting the MATN3 gene in various cancers." (PMID 41004439, 2025). "We conducted Kaplan-Meier survival analyses to compare the prognosis between high and low MATN3 expression groups across various cancers." (PMID 41004439, 2025). "Based on previous studies, our study explored the influence of MATN3 on cancer from a broader perspective." (PMID 39991588, 2025). "The expression of immune checkpoint genes is closely related to the efficacy of do immunotherapy for cancer, so we explored the correlation between immune checkpoint genes, immunoregulatory genes and MATN3 expression." (PMID 39991588, 2025). "Our comprehensive pan-cancer analysis further corroborates the link between elevated MATN3 expression and poor prognosis across multiple cancer types, emphasizing its potential as both a therapeutic target and a diagnostic biomarker." (PMID 41004439, 2025).
cancer (continued). "Given its impact on prognosis, further detailed research on MATN3 in these cancers is crucial for understanding its biological roles and therapeutic potential." (PMID 41004439, 2025). "Our findings advocate for further clinical investigations into α-Pinene’s therapeutic potential, particularly focusing on its impact on MATN3 and related pathways in diverse cancer contexts." (PMID 41004439, 2025). "Utilizing publicly available cancer genomic databases, we conducted a comprehensive analysis of MATN3 expression across multiple cancer cohorts." (PMID 41004439, 2025). "We examined its association with cancer diagnosis, prognosis, molecular typing, immune subtyping, methylation, drug sensitivity, and immune infiltration, providing insights into the multifaceted role of MATN3 in cancer." (PMID 39991588, 2025). "This step was crucial to understanding the clinical significance of MATN3 expression levels in cancer prognosis." (PMID 41004439, 2025). "The reduced expression of MATN3 in specific cancer types like KICH, KIRP, and LUSC raises intriguing questions about its biological function and its potential as a therapeutic target." (PMID 41004439, 2025). "To further elucidate the expression patterns of MATN3 in various cancers, we utilized the Cancer Cell Line Encyclopedia to analyze MATN3 expression across a wide array of cancer cell lines." (PMID 41004439, 2025). "Following the elucidation of the relationship between MATN3 expression and immune cell infiltration across various cancer types, our research further explored the correlation between MATN3 and key immune regulatory genes." (PMID 41004439, 2025). "The reduced expression in specific cancer types raises intriguing questions about MATN3’s biological roles and highlights the importance of a nuanced, cancer-specific approach when considering therapeutic targeting." (PMID 41004439, 2025). "In our pan-cancer analysis, utilizing extensive cancer genomic and transcriptomic datasets, we observed a notable dichotomy in MATN3 expression." (PMID 41004439, 2025). "In the final phase of our investigation into MATN3’s role in cancer, an interaction network was constructed using the STRING database, focusing on proteins related to MATN3." (PMID 41004439, 2025). "Our study combines in vitro experiments with comprehensive pan-cancer bioinformatics analysis, providing evidence for the role of MATN3 in cancer progression." (PMID 41004439, 2025). "We also explored the relationship between MATN3 and the infiltration of six types of immune cells, and we found that four types of cancer types, BRCA-Luminal, LIHC, LUSC, and PRAD, were significantly correlated with all six types of immune cells." (PMID 39991588, 2025). "This complexity underscores the necessity of a nuanced approach to targeting MATN3 in cancer therapy, considering the variable expression and potential contrasting effects across different cancer types." (PMID 41004439, 2025). "Kaplan-Meier survival analysis is performed to understand the effect of MATN3 on Prognostic value in patients with different cancer types." (PMID 39991588, 2025). "Our analysis revealed a striking variation in MATN3 expression among different cancer types at the cellular level." (PMID 41004439, 2025). "In this study, multiple databases were used to analyze the differential expression, diagnostic value, prognostic value, methylation, immune infiltration and enrichment pathway of MATN3 in a variety of cancer types." (PMID 39991588, 2025). "MATN3 shows a strong positive correlation with immune genes in cancers including LIHC, PAAD, COADREAD, and PRAD." (PMID 41004439, 2025). "This study not only underscores the anticancer potential of α-Pinene but also establishes MATN3 as a critical target and biomarker across a spectrum of cancers." (PMID 41004439, 2025). "Of the many EMT- and ECM-associated factors, matrilin-3 (MATN3), and extracellular matrix protein 2 (ECM2) have been related to cancer metastases." (PMID 38322121, 2024).
cancer (continued). "Reduction of HOXB2 and the HOXB2/MATN3/ECM2 transcriptional axis correlated with poor survival in patients with various cancers." (PMID 38322121, 2024). "Our findings unveiled that MATN3 expression was distinctly elevated in GC, and high MATN3 levels were related to cancer development and inferior prognostic results." (PMID 34900024, 2021). "MATN3 is correlated with patient survival in several cancers, particularly in gastric cancer, where it may play a pivotal role." (PMID 41004439, 2025). "Notably, CXCL12 shows a positive correlation with MATN3 in most cancers, suggesting a potential link between MATN3 and CXCL12." (PMID 41004439, 2025). "While the overall mutation rate remains relatively low, specific mutations within critical domains like the vWFA domains could potentially impact MATN3’s functional interactions and contribute to its dysregulation in cancer." (PMID 41004439, 2025). "High expression of MATN3 predicted poor prognosis in most cancer types." (PMID 39991588, 2025). "Based on TCGA and GTEx databases, our work found that MATN3 was significantly up-regulated in 15 cancer types, and MATN3 expression was relatively high in a variety of cancer types in relatively high T stage, relatively high N stage, relatively high M stage, and higher histologic grading." (PMID 39991588, 2025). "Three indicators, OS, DSS, and PFI, were used to evaluate MATN3 and cancer prognosis." (PMID 39991588, 2025). "Additionally, Cox proportional hazards regression models confirmed MATN3’s prognostic value, identifying it as a predictor of worse disease-specific survival and progression-free intervals in several cancer types." (PMID 41004439, 2025). "This may provide some entry points for subsequent studies to explore the regulatory pathways of MATN3 in cancer." (PMID 39991588, 2025). "However, MATN3 conversely exhibited lower expression levels in certain cancers such as KICH, KIRP, and LUSC." (PMID 41004439, 2025). "We investigated the role of MATN3 in pan-cancer and validated this result by in vitro experiments." (PMID 39991588, 2025). "In conclusion, this study analyzed the differential expression, diagnostic value, prognostic value, methylation, immune infiltration and enrichment pathway of MATN3 in various cancer types using multiple databases, and MATN3 is expected to be a prognostic and immune biomarker for pan-cancer." (PMID 39991588, 2025). "Notably, an increased expression of MATN3 was negatively correlated with the drug resistance of cancer cells to eribulin mesylate, vinblastine, pipobroman, paclitaxel, and erlotinib." (PMID 35699863, 2022). "In mice Gpc1 deletion alters brain size and leads to increased risk of cancer, however animals show no skeletal phenotype, as is frequently reported for deleted matrix-associated genes; e.g. Matrilin-3." (PMID 30193893, 2019). "Notably, TNFSF4 and ENTPD1 are positively correlated with MATN3 across most cancers." (PMID 41004439, 2025). "The expression of MATN3 was negatively correlated with Dasatinib32, Elesclomol33, Erlotinib34, and Lapatinib35, suggesting that MATN3 may promote the sensitivity of this part of drugs and play a positive role in cancer treatment." (PMID 39991588, 2025). "Conversely, cancers like KICH, KIRP, and LUSC exhibited lower MATN3 expression, hinting at context-dependent functions or distinct regulatory mechanisms." (PMID 41004439, 2025). "This analysis confirmed that high MATN3 expression served as a predictor of worse disease-specific survival (DSS) and progression-free interval (PFI) in several cancers, including STAD, GBMLGG, COAD, CESC, LIHC, ACC, PCPG, and MESO." (PMID 41004439, 2025). "It is evident that most of them are highly expressed in cancer, with ANXA5, SERPINE1, MARCKS, and MATN3 being particularly significant in their expression levels." (PMID 38287304, 2024). "There were widespread amplifications and deletions of five genes (GPX3, RGS2, MATN3, SLC7A2, and SNCG) across pan-cancer." (PMID 35721114, 2022).
cancer (continued). "Additionally, MATN3 tends to positively correlate with genes such as CD276, NT5E, and TMEM173 in most cancers." (PMID 41004439, 2025). "Building on the findings that α-Pinene effectively reduces MATN3 expression in HCC cell lines, we expanded our investigation to explore the expression patterns and potential roles of MATN3 across a broader spectrum of cancers." (PMID 41004439, 2025). "In addition, MATN3, SLC7A2, and SNCG were significantly upregulated in GC compared with para-carcinoma tissues." (PMID 35721114, 2022). "Additionally, our findings suggest that the lack of HOXB2 subsequently downregulates MATN3 and the ECM2 downstream transcriptional network, leading to aggressive cancer progression, EMT-like characteristics, and poor prognosis." (PMID 38322121, 2024). "However, no research has shown that KNG1, FBN1, MATN3, and SERPINC1 play an important role in cancer chemotherapy resistance." (PMID 34737677, 2021).
skeletal dysplasia (5 papers, 2005 to 2023). Any Mendelian diseases that affects growth and development of the skeleton. "Therefore, the molecular cell pathology of MED caused by MATN3 mutations has similarities to skeletal dysplasias caused by mutations in the genes encoding other extracellular matrix structural proteins, particularly PSACH and forms of MED that result from mutations in COMP [Unger and Hecht, 2001]." (PMID 16287128, 2005). "As ER stress is an attractive target to treat skeletal dysplasias including EDM5, we, therefore, used our established luciferase screening assay to determine if these “natural” chemicals were able to reduce pathological ER stress in cells expressing the archetypal V194D matrilin-3 vWFA mutation." (PMID 36675026, 2023). "Although targeting ER stress is an attractive avenue for treatment and has proven successful in the treatment of a related skeletal dysplasia, to date no drugs have proven successful in reducing ER stress in EDM5 caused by the retention of mutant matrilin-3." (PMID 36675026, 2023). "However, it did not alleviate the intracellular retention of mutant matrilin-3, suggesting that it is the intracellular MANF that is of importance in the pathobiology of skeletal dysplasias." (PMID 30543055, 2019).
connective tissue disorder (1 paper, 2025). A disease involving the connective tissue. "Notably, of the 29 children with nFTS with dysmorphic features resembling connective tissue disorders, 7 had VUSs of genes known to be related to connective tissue (BMP4, MATN3, COL2A1, COL11A1, COL1A1, COL1A2, and COL6A3)." (PMID 40524006, 2025).
infection (1 paper, 2024). The state of being infected such as from the introduction of a foreign agent such as serum, vaccine, antigenic substance or organism. "However, the high expression of Matrilin-3 and CRTAC in uninfected cells, which diminishes after infection, contradicts the process of chondrogenesis." (PMID 39467689, 2024). "In uninfected cells, robust expression of Matrilin-3 and CRTAC was evident but lost upon infection." (PMID 39467689, 2024).
myopathy (1 paper, 2025). A disease of the muscle in which the muscle fibers do not function properly. "In addition to the diagnostic challenge, clinically variable myopathy symptoms have also been observed in PSACH-MED patients, particularly those with mutations in genes encoding type IX collagen, COMP, and, more recently, matrilin-3." (PMID 41155349, 2025). "Therefore, this highlights that muscle weakness and myopathy are associated with type IX collagen and COMP mutations but not with matrilin-3 mutations." (PMID 41155349, 2025).
neurological diseases (1 paper, 2022). "One of the most innovative findings of our work is that three biomarkers that are also altered in neurological diseases (CD200R1, α2-MRAP, and MATN3) are among the strongest predictors of a negative outcome in the complete model." (PMID 36012423, 2022).
MATN3 also shares sentences with these, for which no sentence is quoted: skeletal disease (5 papers); genetic diseases (3); dementia (2); metaphyseal chondrodysplasia type Schmid (2); African trypanosomiasis (1); Alzheimer disease (1); amyotrophic lateral sclerosis (1); Arthritis (1); cartilaginous tumors (1); colon adenocarcinoma (1); hand osteoarthritis (1); hematological malignancies (1); Huntington disease (1); ischemia (1); ischemic stroke (1); joint disease (1); lung carcinoma (1); melanoma (1); osteogenesis imperfecta (1); otosclerosis (1); Parkinson disease (1); renal clear cell carcinoma (1); spondylo-epi-metaphyseal dysplasia (1); tuberculosis (1); type 2 collagenopathy (1); type II diabetes (1).